SOX2 (SRY-box transcription factor 2)
Diseases named in the same sentence as SOX2 in open-access papers (continued):
Sharing a sentence is not in itself a finding about the gene and the disease.
breast cancer (continued). "Both OCT4 and Sox2 have been strongly correlated to the acquisition of CSC characteristics in breast cancer cells." (PMID 34830485, 2021). "Depletion of LGR4 resulted in a reduction of SOX2+ breast cancer stem cells, disruption of the Wnt/β-catenin signaling pathway, and a decrease of the tumorsphere formation ability." (PMID 33946652, 2021). "Results showed that TrkA WT-overexpressing cells had significantly higher mRNA levels of SOX2 and MYC, which are two known STAT3 target genes frequently associated with breast cancer cell stemness and aggressiveness." (PMID 34066153, 2021). "The expression signatures of OCT4, SOX2, and NANOG are associated with poor clinical outcomes in breast cancer." (PMID 34064635, 2021). "Another experiment reveals that cancer-associated fibroblasts (CAFs) existing in TME are able to reduce SOX2 expression and suppress stemness in breast cancer via reducing CSC features." (PMID 34769099, 2021). "All patients were primarily subjected to serum AGR2 levelling by ELISA and their breast cancer tissue immunostained for SOX2 and AGR2." (PMID 34567804, 2021). "β-catenin binds POU5F1/OCT4 in embryonic stem cells, it stimulates human NANOG promoter activity and it regulates SOX2 activity in breast cancer cells." (PMID 34199594, 2021). "As one of the four transcription factors that are sufficient to induce pluripotency 51, SOX2 regulates EMT through Wnt signaling in several cancer types including breast cancer 52 and colorectal cancer." (PMID 34646394, 2021). "The LGALS8-AS1/miR-125b-5p/SOX2 reciprocal regulatory loop dyscrasia promoted the migration and invasion of breast cancer cells." (PMID 34745940, 2021). "SOX2 is critical for maintaining the pluripotency of embryonic stem cells and has been credited with the induction and maintenance of breast cancer cell stemness." (PMID 34066153, 2021). "Downregulation of ALG3 reduced, while upregulation of ALG3 increased NANOG, OCT4 and SOX2 expression in breast cancer cells under radiation treatment." (PMID 33931075, 2021). "Positive staining was demonstrated on sections of control human tissues: tonsil for CD44, seminoma for OCT4 and NANOG, skin epidermis for SOX2, breast carcinoma for KLF4, and colon mucosa for c-MYC." (PMID 34685477, 2021). "Taken together, these data showed that inhibition of DNMT activity suppresses tumor growth via regulating FOXO3a/FOXM1/SOX2 signaling in breast cancer." (PMID 31296961, 2020). "Collectively, our findings suggest an important role of the DNMT1/FOXO3a/FOXM1/SOX2 pathway in regulating BCSCs properties, suggesting potential therapeutic targets for breast cancer." (PMID 31296961, 2020). "We further validated the correlation between Snail and Sox2 or angiogenesis-related genes expression in breast cancer patients from the cancer genome atlas (TCGA) and GEO database (NCBI Gene Expression Omnibus)." (PMID 32541667, 2020). "Clinically, we observed a significant inverse correlation between FOXO3a and FOXM1/SOX2/DNMT1 expression levels, and loss of FOXO3a expression or increased expression of FOXM1, SOX2, and DNMT1 predicted poor prognosis in breast cancer." (PMID 31296961, 2020). "IKKβ targeting reduces breast cancer mammosphere formation and tumourigenicity, and positively regulates Lin28B and SRY (sex determining region Y)-box 2 (SOX2) to promote breast cancer stemness and reduces breast GD2+ TICs, thereby reducing metastasis." (PMID 32823550, 2020). "Previous work on the crucial role of SOX2 in breast cancer cell migration showed that SOX2 upregulation in hypoxic conditions facilitated NEDD9 transcription and subsequent activation of HIF-1α expression." (PMID 32913192, 2020).
breast cancer (continued). "Elevated SOX2 expression in epithelial TICs (e.g. lung and breast cancers) had been described to be responsible for evasion of complement surveillance." (PMID 30517668, 2020). "SOX2 expression is found across a wide range of human cancers such as breast cancer, lung cancer, and esophageal cancer." (PMID 32104175, 2020). "Inhibition of DNMT activity suppressed tumor growth via regulation of FOXO3a/FOXM1/SOX2 signaling in breast cancer." (PMID 31296961, 2020). "Among them, overexpression of SOX2 results in abnormal stem cell self-renewal in breast cancer cells, which aids in tumor progression and contributes to poor clinical outcomes in breast cancer." (PMID 31979292, 2020). "In the interplay between CSCs and TAMs, a putative role for the signal transducer and activator of transcription 3 (STAT3) pathway has been demonstrated in breast cancer models via a novel paracrine EGFR/Stat3/Sox-2 axis." (PMID 32630659, 2020). "Sox2 also maintains the phenotype of breast cancer stem/progenitor cells by activating Wnt signaling, thereby rendering EsR+ breast cancer cells insensitive to tamoxifen treatment." (PMID 33234169, 2020). "Overexpression of Snail induced endothelium generation of breast cancer cells in a Sox2-dependent and VEGF-dependent manner." (PMID 32541667, 2020). "For example, SOX2 expression is correlated with worse prognosis in breast cancer and gastric cancer." (PMID 32104175, 2020). "Specifically, the expression of NANOG and SOX2, which are demonstrated to drive tumorigenesis and metastasis in breast cancer, was 5-fold higher in CD44−/low/CD24−/low cells from luminal cell lines compared to CD44high/CD24−/low cells from Hs578T." (PMID 32423137, 2020). "Many studies have also demonstrated that Stat3 phosphorylation and activation upregulate the expression of cMyc and Sox2, which promote the self-renewal of breast cancer cells." (PMID 32630026, 2020). "The therapeutic potential of targeting SOX2-driven CSC supports the clinical use of iadademstat as a novel anti-SOX2 epigenetic breast cancer therapy, particularly in SOX2-enriched luminal-B and HER2-positive subtypes." (PMID 32191225, 2020). "Biologically, FBXW2 promotes tumor sphere formation by upreglating SOX2 via inducing MSX2 degradation, while MLN4924 sensitizes breast cancer cells to tamoxifen by depleting SOX2 via targeting the FBXW2-MSX2 axis." (PMID 31748974, 2020). "SOX2 has been reported to be commonly expressed in many human cancers, such as breast cancer, lung cancer, esophageal cancer, and CRC." (PMID 32104175, 2020). "To summarize, Snail-mediated breast cancer cell stem-like phenotypes and endothelium generation is dependent on Sox2." (PMID 32541667, 2020). "Development of tamoxifen resistance had been reported to occur due to SOX2-dependent activation of Wnt/β-catenin signaling pathway in breast cancers." (PMID 30517668, 2020). "We further investigated the clinical significance of DNMT1/FOXO3a/FOXM1/SOX2 signaling in breast cancer." (PMID 31296961, 2020). "Since Snail transdifferentiated breast cancer cells into EC, and triggered cancer stem-like phenotypes through Sox2, we investigated the role of Sox2 in Snail-mediated generation of breast cancer cells into EC." (PMID 32541667, 2020). "The Hollern Squamous Breast Tumor gene set is positively correlated with POU5F1 and SOX2 gene expression and consists of genes that have high expression in mammary tumors of squamous epithelium histology." (PMID 32899474, 2020). "Sox2 has been shown to increase CSCs, enhance tumor cell invasion, and promote tamoxifen resistance in breast cancer lines." (PMID 32098183, 2020). "High levels of SOX2 expression with endocrine treatment failure and poor relapse-free survival were observed in a cohort of ER-positive patients with breast cancer who had received tamoxifen therapy." (PMID 30517668, 2020).
breast cancer (continued). "Here, we tested the ability of the clinically proven inhibitor of the lysine-specific demethylase 1 (LSD1/KDM1A) iadademstat (ORY-100) to target SOX2-driven CSC in breast cancer." (PMID 32191225, 2020). "In breast cancer cell lines, Sox2 increases mammosphere formation, up-regulates CCND1, the cyclin D1-encoding gene, thus facilitating the G1/S transition of the cell cycle, activates the WNT signaling pathway and the epithelial-to-mesenchymal transition." (PMID 33553286, 2020). "Iadademstat blocked CSC-driven mammosphere formation in breast cancer cell lines that are dependent on SOX2 expression to maintain their CSC phenotype." (PMID 32191225, 2020). "For example, our laboratory demonstrated that SIX2 overexpression in breast cancer cells leads to efficient metastatic colonization in the lung via its ability to induce a CSC phenotype through upregulation of SOX2." (PMID 32391382, 2020). "In a process that is not mutually exclusive, the differentiation genes that are directly controlled by LSD1 can indirectly inhibit the expression of SOX2 that confers stem cell-like traits to breast cancer cells." (PMID 32191225, 2020). "Another study in breast cancer found that Sox2 and β-catenin synergistically promoted the transcription of CCND1, resulting in enhanced proliferation and tumorigenesis." (PMID 33302540, 2020). "The gene c-myc is over-expressed in breast cancer and SOX2 and NANOG are critical regulators of self-renewal, as well as pluripotency of embryonic stem cells, and are CSC markers." (PMID 33375053, 2020). "Together, these results suggested that the regulation of CSC properties by the FOXO3a/FOXM1 axis is mediated by SOX2 in breast cancer cells." (PMID 31296961, 2020). "Unfavorable prognostic value of Sox2 (at >42% cutoff) in feline mammary carcinomas (multivariate survival analyses, N = 180 cats)." (PMID 33553286, 2020). "Expected staining patterns were demonstrated in the human positive control tissues: seminoma for OCT4 and NANOG, normal skin for SOX2, breast carcinoma for KLF4, and normal colon for c-MYC." (PMID 32019273, 2020). "Resveratrol suppressed expression levels of cyclin D1, c-Myc, MMP-2, MMP-9 and Sox2, which were upregulated by CAFs in breast cancer cells." (PMID 30791624, 2019). "IL-6 signaling was shown to cooperate with a hypoxic TME conditions to induce expression of C/EBPδ and other “stemness” promoting factors such as Nanog, Sox2 and Klf4 in breast cancer stem cells." (PMID 31450577, 2019). "Here, we find that upregulation of SOX2 facilitated hypoxia-induced breast cancer cell migration via regulation of NEDD9 transcription and expression." (PMID 31462898, 2019). "To ensure the expression pattern of SOX2 protein in hormone therapy-resistant breast cancer tissues, we determined SOX2 expression by IHC." (PMID 30759864, 2019). "Increased cancer stem cell content during development of resistance to tamoxifen in breast cancer is driven by multiple signals, including Sox2-dependent activation of Wnt signalling." (PMID 30622340, 2019). "Western blot confirmed the successful down-regulation of PTX3 in both breast cancer cells which correlated with decreased expression levels of Oct4, Sox2, and N-cadherin but increased expression of E-cadherin compared with control." (PMID 30740360, 2019). "Disturbing the TRIB3-AKT interaction suppresses BCSCs by accelerating FOXO1 degradation and reducing SOX2 expression in mouse models of breast cancer." (PMID 31844113, 2019). "SOX2 was also shown to be relevant in the development of the stemness properties of breast cancer cells." (PMID 31462898, 2019). "This was accompanied by an increase in breast cancer stemness (SOX2, OCT4, and NANOG levels) and significant increase in the levels of key drug transporters (ABCG2, ABCB1, and ABCC1)." (PMID 31867270, 2019).
breast cancer (continued). "A previous report has indicated that SOX2 is overexpressed in tamoxifen-resistant cells and that it confers stem cell-like and resistance phenotypes in breast cancer cells." (PMID 30759864, 2019). "SOX2 expression has been shown to positively correlate with the cancer cell stemness of solid tumors, including breast cancer, and knockdown of SOX2 decreases invasiveness and cancer cell stemness." (PMID 31844113, 2019). "The downregulation of tumor suppressor Maspin promoted anchorage-independent growth of breast cancer, whereas suppression of SOX2 oncogenes reduced breast cancer cell proliferation." (PMID 31597272, 2019). "As in other studies, our primary observations are that hypoxia increases the SOX2 protein level in breast cancer cells and silencing of SOX2 suppresses the increased cell migration rate stimulated by hypoxia." (PMID 31462898, 2019). "The SOX2/miR-181a-5p, miR-30e-5p/TUSC3 axis is also identified as being closely linked with the proliferation and migration of breast cancer cells." (PMID 31462898, 2019). "In accordance with the results in our study, a prior study has revealed that miR-200c-3p downregulation results in the paclitaxel resistance of breast cancer cells through targeting SOX2." (PMID 31516388, 2019). "This study reveals SOX2 as a critical positive regulator of breast cancer cell migration under hypoxia." (PMID 31462898, 2019). "Roles for SOX2 have been extensively studied in several types of cancer, including colorectal cancer, glioblastoma and breast cancer, with particular emphasis placed on the roles of SOX2 in cancer stem cell." (PMID 31365524, 2019). "SOX2 is a powerful transcription factor that shows higher expression in several cancers, however, its role in hypoxia-induced breast cancer cell migration remains largely elusive." (PMID 31462898, 2019). "Tamoxifen-induced TARBP2 further stabilizes SOX2 protein to enhance desensitization of breast cancer cells to tamoxifen, while similar to TARBP2, its induction in cancer cells was also observed in metastatic tumor cells." (PMID 30759864, 2019). "qRT-PCR revealed that GREM1 OE or rhGrem1 increased the expression of transcriptional regulators YAP, TAZ, SOX2, and OCT4, which have been implicated in maintaining breast cancer stemness." (PMID 31533776, 2019). "Our work indicates that TRIB3 links stress signals to breast cancer stemness through the coordination of FOXO1 and SOX2 in breast cancer with high TRIB3 expression." (PMID 31844113, 2019). "In line, proNGF binds TrkA and sortilin in breast cancer, inducing the Sex Determining Region Y-box 2 (Sox2) and conferring higher invasiveness to CSCs in a p75NTR-independent manner." (PMID 31812953, 2019). "SOX2 promotes tumor metastasis by stimulating epithelial-mesenchymal transition via WNT-β catenin pathway in breast carcinomas." (PMID 31508790, 2019). "The expression of SOX2 in eight breast cancer cell lines (five TNBC cell lines, three NTNBC cell lines) and two mammary normal cell lines were detected by qRT-PCR." (PMID 30186173, 2018). "SRY-related HMG box-containing transcription factor-2 (SOX2) is one of these abnormal expressed genes in many cancers including breast cancer." (PMID 30186173, 2018). "Further, DDX49 seems to promote the stemness of breast cancer stem cells by regulating the expression of proteins such as Oct3/4 and Sox-2 and promoting disease progression." (PMID 29618122, 2018). "For example, lncRNA HOTAIR tightly regulates the proliferation, colony formation, migration and self-renewal capacity of breast cancer CSCs, and specifically inhibits miR-34a, which leads to the upregulation of Sox2 protein." (PMID 30482236, 2018). "SOX2 was revealed to be amplified and overexpressed in gastric cancers, and depletion of SOX2 markedly inhibited cell proliferation and tumor growth in breast cancer through downregulating CCND1 and PARP27." (PMID 30108202, 2018).
breast cancer (continued). "Functionally, the gain and loss-of-functional experiments revealed that LINC00511 promoted the proliferation, sphere-formation ability, stem factors (Oct4, Nanog, SOX2) expression and tumor growth in breast cancer cells." (PMID 30482236, 2018). "Previous studies reported that transcription factor SRY (sex-determining region Y)-box 2 (Sox2) is an interaction partner of β-Catenin in breast cancer and mouse embryonic stem (mES) cells 10,27." (PMID 29674637, 2018). "Another previous study demonstrated that the upregulation of SOX2-activated LncRNA PVT1 expression promotes breast cancer cell growth and invasion." (PMID 29463902, 2018). "We have previously identified a novel phenotypic dichotomy in breast cancer (BC) based on the response to a SRR2 (Sox2 regulatory region 2) reporter, with reporter responsive (RR) cells being more tumorigenic/stem-like than reporter unresponsive (RU) cells." (PMID 29401647, 2018). "High SOX2 expression was related to adverse breast carcinoma profile, less differentiated subtype and poor disease outcome." (PMID 29963272, 2018). "In human breast cancer samples the levels of TUSC3 protein are inversely correlated with those of SOX2 protein." (PMID 28288641, 2017). "Upregulation of OCT4, Sox2 and Nanog has been reported in many cancers such as prostate and breast cancer." (PMID 28380428, 2017). "We also found that CHD7 and SOX2 (3q26) were likely cogained/amplified (P < 0.0001) in breast cancer." (PMID 28649742, 2017). "Together, these in vivo findings support the important roles of SOX2 in promoting metastasis of breast cancer cells." (PMID 28288641, 2017). "Endocrine-sensitive or -resistant breast cancer cell lines were used to examine the expression of the stem cell gene SOX2, and the Wnt effector genes AXIN2 and DKK1 using quantitative PCR analysis." (PMID 28929082, 2017). "The ER− endocrine-resistant breast cancer lines (generated by fulvestrant treatment) showed significant upregulation of SOX2 expression as compared to the ER+ cell lines." (PMID 28929082, 2017). "In this study, we found that fentanyl induced stemness and EMT in MCF-7 and MDA-MB-231 breast cancer cells by analysis of sphere formation, expression of stemness markers (Sox2, Oct4) and EMT markers (N-cadherin, E-cadherin and Vimentin)." (PMID 28798691, 2017). "In this study we investigate the role of SOX2 in breast cancer metastasis using multiple in vitro and in vivo assays including cell culture, shRNA-mediated knockdown, wound healing, colony formation, transwell chamber, xenograft and tail vein injection." (PMID 28288641, 2017). "Previous studies revealed that approximately 16% of breast cancer patients exhibit SOX2-positive expression in clinical samples, and SOX2 is expressed in the early stage of breast tumours." (PMID 28288641, 2017). "Another study showed that the coculture of adipocytes and breast cancer cells stimulates the production of various cytokines that promote cancer stemness through the Src/SOX-2/miR-302b signaling pathway." (PMID 28337221, 2017). "The pathway linking VEGFA to Sox2 upregulation, miR-452 loss and SNAI2 induction is supported by our analysis of two major data sets including over 2500 primary human breast cancers." (PMID 28504716, 2017). "Together, these in vitro results demonstrate that high levels of SOX2 protein are critical for migration and invasion of breast cancer cells." (PMID 28288641, 2017). "The PP2-mediated increase in Qa-2 expression levels occurred concomitantly with a reduction in Sox2 expression and the number of CD44high/CD24med/low cells, emphasizing again the inverse relationship between Qa-2 and stemness in breast cancer cells." (PMID 28740236, 2017). "All together, these data indicate that P63 and SOX2 have pivotal role in breast cancer and therefore are potential to be used as specific biomarkers." (PMID 29527291, 2017).